PPT2-EGFL8 (PPT2-EGFL8 readthrough (NMD candidate))
Gene: Protein-coding gene on chromosome 6 (32,153,845 to 32,171,978, forward strand). Ensembl gene ENSG00000258388.
Genetic constraint (gnomAD): Missense variants: 244 observed, 365.21 expected, observed/expected ratio (o/e) 0.67, 90% interval 0.6 to 0.74. Synonymous variants: 118 observed, 153.43 expected, observed/expected ratio (o/e) 0.77, 90% interval 0.66 to 0.9.